MYD88 (MYD88 innate immune signal transduction adaptor)
Diseases named in the same sentence as MYD88 in open-access papers (continued):
Sharing a sentence is not in itself a finding about the gene and the disease.
infection (continued). "We investigated the expression of the Toll signaling cascade (Toll receptors-MyD88-Dorsal-defensin) upon SRBSDV infection in planthopper S. furcifera." (PMID 38865374, 2024). "MyD88 was also required to control chronic P. aeruginosa infection in a murine model, where complete deletion of MyD88 resulted in severe and lethal lung pathology following infection." (PMID 39015565, 2024). "During the onset of infection, B. abortus modulates the response of invaded macrophages, impairing the activation of MyD88-dependent signaling pathways and reducing the inflammatory activity triggered by pathogen recognition." (PMID 38464511, 2024). "As shown by survival curves, MyD88 mutant flies began to die on the third day post-infection (dpi), and almost half of them would succumb to T. marneffei injection in the first 5 days." (PMID 39239739, 2024). "Since MyD88 is a signal-transducing molecule for both the IL-18 receptor and the IL-1 receptor, the role of each of these receptors on resistance to infection was studied." (PMID 38535182, 2024). "In this study, we reveal that the infection of S. furcifera by SRBSDV activates the upstream Toll receptors expression but suppresses the downstream MyD88-Dorsal-defensin cascade, thereby antagonizing the Toll antiviral immune response." (PMID 38865374, 2024). "Infection of Laodelphax striatellus with rice stripe virus directly activated the Toll pathway, and the expressions of Tube, MyD88, and Dorsal genes were upregulated in viruliferous planthoppers." (PMID 39336611, 2024). "Only MyD88 and Toll mutant flies succumb to this challenge whereas most wild-type flies appear to clear the infection at the low dose used in our experiments." (PMID 39239739, 2024). "Consistent with previous studies, we observed a significant increase in the expression of Tlr2, Myd88 and Nod2 after infection, indicating that both types of E. faecium can activate these signalling pathways." (PMID 38951957, 2024). "After TLR4 recognizes LPS infection, it activates intracellular tail-like structures, recruits myeloid differentiation factor MyD88, activates NF-κB, and further releases pro-inflammatory cells." (PMID 37268931, 2023). "This response was lost in total Myd88−/− mice where mice displayed an inability to control infection, with 7/10 mice succumbing to infection." (PMID 37244938, 2023). "Our data demonstrate that F. tularensis suppresses TLR2- and MYD88-dependent activation of p38 early during infection in a TolC-dependent manner." (PMID 37404047, 2023). "Mice infected with R20291 quickly succumbed to infection 2 days after spore inoculation, whereas all MyD88−/− mice infected with ST1-75 survived the experiment with minimal weight loss or disease scores." (PMID 37523264, 2023). "We previously showed that infection with highly virulent Ehrlichia japonica (E. japonica) induces liver damage and fatal ehrlichiosis in mice via deleterious MyD88-dependent activation of CASP11 and inhibition of autophagy in macrophage." (PMID 38022511, 2023). "Toll-like receptor (TLR)/MyD88 is a conserved innate cellular immune signaling pathway against pathogens infection." (PMID 37909781, 2023). "Platelets express functional TLR2/4 and MyD88, which participate in platelet responsiveness to infection." (PMID 37885890, 2023). "MYD88-deficient mice were unable to maintain protection against infection with the LVS ΔtolC mutant, identifying MYD88 as critical for host defense and a key target for F. tularensis subversion." (PMID 37404047, 2023). "TLR2 and its adapter protein MYD88 localize to the chlamydial inclusion during infection suggesting the ligand is sampled within the inclusion during infection." (PMID 37662000, 2023). "We, therefore, examined the contribution of MyD88 to CASP11 activation following infection of HCs with E. japonica." (PMID 38022511, 2023).
infection (continued). "Consistent with reduced IFNγ expression, the mRNA induction of Nos2, Gbp1, Gbp2, Gbp4, Gbp5, Ido1 and Acod1 was severely impaired in the spleens of Myd88−/− mice after intraperitoneal infection." (PMID 36479617, 2023). "TLR2 typically transmits signals through the cytoplasmic adaptor protein MyD88, leading to NFκB activation and proinflammatory gene expression, which protects multicellular organisms from infection." (PMID 37298614, 2023). "Early recognition of F. tularensis by TLR2 and MYD88 contributes to host protection during both macrophage and in vivo infection, with MYD88 playing a more critical role in vivo." (PMID 37404047, 2023). "In contrast, not only did the MYD88−/− mice succumb to infection faster with the WT LVS, but also the virulence of the ∆tolC mutant was fully restored." (PMID 37404047, 2023). "Upon pathogenic infection, MyD88 undergoes aggregation to form a dimer, which is crucial for its activation and downstream signal transduction in the TLR-MyD88 signalling pathway." (PMID 37332205, 2023). "No increase was observed in the transcription of Toll-like receptors (TLR2, TLR4, TLR6) and TLR adaptor protein MYD88 during infection with any of the examined S. suis strains." (PMID 38276150, 2023). "Meanwhile, our research provides a reference dataset for in-depth studies on the molecular mechanisms of (TLR1-2) - MyD88 - FADD - Caspase 8 mediating apoptosis pathway in bony fish after the bacterial pathogen infection." (PMID 37056759, 2023). "The infection with Salmonella statistically significantly induced adaptor protein MyD88 mRNA, but this induction was significantly lower for previous association with either RP36 or RP37 B. boum strains." (PMID 38003758, 2023). "Further, by examining the signaling events, we determined that silencing either MyD88 or TLR-9 reduces the production of proinflammatory cytokines in DCs during LdCen−/− infection." (PMID 37111420, 2023). "In the present study, we also observed that the expression of the heterotrimeric death domain complex (Myd88, Pelle, and Tube) was consistently lower after infection compared to the pre-infection levels." (PMID 37623411, 2023). "We investigated here the role of MyD88 signaling in HCs during infection with E. japonica using primary cells from wild-type (WT) and MyD88-/- mice, along with pharmacologic inhibitors of MyD88 in a murine HC cell line." (PMID 38022511, 2023). "PTX3 protein levels determined by ELISA in lung homogenates (C) and serum (D) collected 36 hr post-infection in WT, Il1r−/− and Myd88−/− mice (n = 7–8)." (PMID 37222419, 2023). "Analysis of the TLR signaling pathway in preleukemic precursor B cells of Pax5+/− mice exposed to infections revealed a decrease in the expression of the adaptors Myd88 and Tirap, as well as the downstream transcription factor Nfkb1a." (PMID 37620322, 2023). "Several viruses, such as influenza A virus and human respiratory syncytial virus, have also been shown to activate p38 MAPK within 10 min of infection through recognition of pattern recognition receptors by toll-like receptor 4 and MyD88 during virus entry." (PMID 35463647, 2022). "In the case of Mtb, induced production and secretion of IL-36γ was observed upon infection of host macrophages with the Mtb reference strain H37Rv, dependent upon the Toll-like receptor and MyD88 pathways." (PMID 36242542, 2022). "The infiltrating CD11b+ cell number and the neutrophil proportion were much smaller in MyD88−/− than those in IFN-γR−/− at the site of infection." (PMID 36190414, 2022). "Despite the similar parasite number, a lower inflammatory response was induced in MyD88−/− mice compared with that of IFN-γR−/− mice upon 5-ASKH infection." (PMID 36190414, 2022). "Compared to the control group, phosphorylated NF-κB and MyD88 protein expression in RAW264.7 cells was significantly increased by LPS infection, while MccJ25 treatment significantly decreased p-NF-κB and MyD88 protein expression after LPS challenge for 3 h." (PMID 35250983, 2022).
infection (continued). "In 5-ASKH infection, MyD88−/− mice developed significantly smaller lesions with fewer neutrophil recruitment than IFN-γR−/− mice, together with the equivalent parasite number, indicating critical roles of MyD88 signaling in lesion development." (PMID 36190414, 2022). "The minimum lethal dose of S. aureus was adjusted for MyD88-KO mice due to increased sensitivity to infection, which resulted in similar blood bacteria loads in vehicle-treated mice from all three strains." (PMID 36439136, 2022). "Resembling what was described during primary infection, Myd88/Trif -/- mice showed less recruitment of neutrophils to the lung and airways, while Mavs-/- mice showed lower numbers of inflammatory monocytes in the lung." (PMID 35108347, 2022). "Myeloid differentiation primary response protein 88 (MyD88) is a canonical adaptor for the Toll-like receptor family which has crucial roles in host defense against infection by microbial pathogens." (PMID 36032091, 2022). "In a subsequent study, the working group further examined the influence of the intestinal microbiota on ILC1 and ILC3 in MyD88−/− and MyD88+/+ mice after oral infection with T. gondii." (PMID 36430676, 2022). "Direct infection of BMDCs by Toxoplasma gondii induced IRE1α activation via MyD88-dependent TLR signaling, with decreased cross-presentation on XBP1 KO with partial IRE1α disruption." (PMID 35446348, 2022). "At different times (15, 30, 45 and 60 min) after infection, the protein levels of MyD88 and NLRP3 and the phosphorylation of Iκbα and p65 were significantly upregulated compared with those at 0 min (P < 0.01)." (PMID 35578336, 2022). "We would postulate that the LPS-derivative MPLA and MyD88-activating agonist CpG can induce similar alterations to the epigenetic landscape of myeloid progenitors and long-term infection resistance, which warrants future investigation." (PMID 36439136, 2022). "Through these receptors, the MYD88 pathway converts infection signaling into bone-resorption signaling." (PMID 36333322, 2022). "Activation of downstream NF-κB signaling through MyD88 results in the production of pro- or anti-inflammatory cytokines as well as type I IFNs, which antagonize the infection of bacterias or single-stranded RNA virus." (PMID 36032091, 2022). "The high level of infectious rhinitis, with accumulation of purulent mucus-containing exudate in the conchi of MyD88 KO mice in 7 days after high-dose inoculation, allowed to mimic the progressive evolution of the infection observed in human infants." (PMID 35395059, 2022). "Similar to findings for MYD88, expression of representative genes upon infection with wild-type Mtb or PDIM or ESX-1 mutants was entirely lost in Tlr2-/- BMDM." (PMID 34755600, 2021). "In the myd88-/- larvae, the number of L-plastin-positive cells at the site of infection was significantly lower (10.2 ± 1.8)." (PMID 33559740, 2021). "In the myd88-/- larvae, the infection developed more rapidly resulting in an increased infection rate at 4 dpi." (PMID 33559740, 2021). "Taken together, these data confirm that endosomal TLR2, TLR7 and MyD88 colocalize to Bb-containing phagosomes to facilitate recognition of bacterial ligands and early response to infection." (PMID 34000990, 2021). "In MyD88 knock-out mice, intranasal infection with 104 CFU of virulent B. pertussis resulted in strong lung inflammation, exacerbated bacterial growth in the lungs, weight loss and 100% mortality within 10 days after infection." (PMID 33807962, 2021). "MYD88 signalling is critical in maintaining IL-12 levels, but the up-regulation of miR-466i after SbRLD infection lead to the degradation of MYD88 and subsequently a reduction in IL-12 levels." (PMID 34218829, 2021). "Tissue content of TNF-α was not altered, but other cytokines or proinflammatory modulators were increased at different times of infection, namely, IL-1β, MyD88, and RAGE." (PMID 34303703, 2021).
infection (continued). "Silencing MyD88 which is activated by TLR7 or silencing MAVS which is activated by MDA5 in microglia exposed to exosomes secreted by microglia during TMEV infection reduced the expression of type I interferons." (PMID 34485270, 2021). "The breakdown of all DE transcripts by type was remarkably similar for infection of wild type and MyD88 KO mice." (PMID 33622246, 2021). "The differences in IL-1β levels and cell death between wild-type Mtb and the ΔpknF mutant were abolished in TRIF/Myd88-/- BMDMs following ΔpknF mutant infection." (PMID 34324582, 2021). "This is consistent with our earlier observations of an increased bacterial burden in myd88-/- larvae using a blood island infection model." (PMID 33559740, 2021). "Apparently, there is a difference in Myd88 dependency between initial and long-term leukocyte response to Mm infection." (PMID 33559740, 2021). "We found that the mutants elicited markedly enhanced expression of a cluster of inflammatory genes induced late after infection; expression was strictly dependent upon MYD88 and TLR2." (PMID 34755600, 2021). "At 4 dpi, the infection in the tail fin has resulted in the formation of an initial stage granuloma, which in myd88+/+ larvae was observed as a large local accumulation of L-plastin-positive cells (35.4 ± 4.2) at the site of the infection in the tail fin." (PMID 33559740, 2021). "More proximal loss-of-function defects, such as those found in TLR3 or in the adaptors MyD88 and IRAK-4, are associated with a restricted cadre of infections." (PMID 34199501, 2021). "We believe this apparent discrepancy is due to the fact that during infection the MyD88-dependent inflammation and phagocytes activation are necessary in order to release LPS from the bacterial membrane in amounts sufficient to achieve B1 cells activation." (PMID 34449811, 2021). "We show that the inflammatory responses mediated by Myd88 affect the number of leukocytes present at the site of infection as well as the acidification of intracellular compartments." (PMID 33559740, 2021). "In various fish, myd88 has been detected to have high transcripts levels after pathogens infection, while little is known for fish tradd, ripk-2 and act1 genes." (PMID 33732247, 2021). "While transcripts for parasite secretory proteins were amongst the most highly expressed T. gondii genes during infection, no differentially expressed parasite genes were identified when comparing infection in MyD88 knockout and wild type host BMDM." (PMID 33622246, 2021). "In general, infection with H. felis resulted in a decreased diversity index (statistically significant for WT at 6 months (p < 0.05); Myd88−/− at 1 month (p < 0.05) and 3 months (p < 0.01); TrifLps2 at 3 months (p < 0.05); and DKO at 3 months (p < 0.01)." (PMID 33477306, 2021). "In the present study, the expression of il-8 and il-1β were significantly upregulated in the head kidney and spleen at 30 d after infection, which was accompanied with the increased expression of nf-κb and myd88." (PMID 35052548, 2021). "DC, neutrophil, and macrophage cell numbers were overall similar between MyD88+/+ and MyD88-/- mice at day 7 post-infection." (PMID 34597344, 2021). "Increased expression levels of TLR3 and/or TLR7, RIG1, and MyD88 genes were detected in response to infection, resulting in the transcriptional upregulation of IFN-λ1 in both ALI-PREC cultures and tracheal epithelia." (PMID 34935443, 2021). "Knockdown of the transcription of either MYD88 or IRAK1 abolished the production of infection-induced proinflammatory cytokines and chemokines, such as interleukin 8 (IL-8), IL-1ꞵ, and IL-2." (PMID 34933448, 2021). "MyD88 KO mice were treated with an antibiotic cocktail in their drinking water one week prior to, and throughout infection." (PMID 34597344, 2021). "Transcripts for the bradyzoite antigen BAG1 were less abundant during RH infection compared to PTG infection in both wild type and MyD88 KO." (PMID 33622246, 2021).
infection (continued). "At 4dpi, the difference in infection level between myd88+/+ and myd88-/- larvae was maximal with a bacterial volume of 69·103 (± 1.6·103) μm3 and 328·103 (± 52·103) μm3, respectively." (PMID 33559740, 2021). "At 4 dpi, myd88+/+ larvae show a high number of TUNEL positive cells (48.7 ± 3.6) throughout the site of infection." (PMID 33559740, 2021). "KO of MyD88 showed an even greater reduction in both IL-6 and TNFα secretion from 3 to 48 h post infection." (PMID 34280250, 2021). "We monitored the response to LPS exposure with the aim to understand how B cell-specific MyD88 signaling impacts LPS-driven infection in midgestation." (PMID 34685673, 2021). "When Neu1 alone was overexpressed followed by infection, it led to the activation of the MyD88-pathway possibly due to TLR4-desialylation." (PMID 33763070, 2021). "To broadly characterize the intestinal immune response to Toxoplasma, we employed a commercial multiplex protein array containing 111 immune mediators to gain insight into the influence of MyD88 during infection in the intestinal mucosa." (PMID 34597344, 2021). "The MyD88-mediated innate immune response has been already proven to be primarily important for protection against microbial pathogen infection via the induction of inflammatory cytokine production." (PMID 34349744, 2021). "Regarding lncRNAs, greater abundance of mir17hg was common to both wild type and MyD88 KO infection by RH and PTG." (PMID 33622246, 2021). "In order to investigate the presence of leukocytes at the site of infection in myd88-/- zebrafish, we performed Lcp1/L-plastin immunostaining at 4 dpi for visualization of all leukocytes." (PMID 33559740, 2021). "Siva1–205 and Nfkb1–210 lncRNAs were of higher abundance during RH infection of wild type and Myd88 KO macrophages." (PMID 33622246, 2021). "The expression of nf-κb and myd88 significantly increased with prolonged infection period, while dietary glutamine further promoted the expression of nf-κb in the spleen." (PMID 35052548, 2021). "A study investigating the involvement of TLR2, TLR4, and MyD88 in pulmonary C. burnetii infection found a different role for these factors according to the site of infection." (PMID 34796128, 2021). "To determine IL-12p40 producing cell populations during in vivo infection of MyD88 KO mice we backcrossed MyD88+/+IL-12p40-eYFP reporter mice with MyD88-/- animals to generate MyD88-/-IL-12p40-eYFP reporter mice." (PMID 34597344, 2021). "MyD88 has been reported to induce MCP-1 release of macrophages after their infection with Listeria monocytogenes." (PMID 34073235, 2021). "We therefore employed RNA sequencing (RNA-seq) to determine the transcriptome of MyD88+/+ and MyD88−/− bone marrow-derived macrophages (BMDM) following infection with T. gondii." (PMID 33622246, 2021). "Both Toxoplasma and microbiota specific CD4+ T cell populations underwent infection-induced expansion in the MyD88+/+ and MyD88-/- lamina propria." (PMID 34597344, 2021). "We show that upon injection of bacteria in the tail fin, a localized infection develops in both myd88+/+ and myd88-/- larvae." (PMID 33559740, 2021). "We found that NK cells from MyD88-deficient mice were unable to upregulate the expression of CD71 and CD98 following infection and these mice exhibited defects in NK cell-mediated viral clearance as displayed by higher viral loads." (PMID 34093543, 2021). "Collectively, our findings revealed multiple pathways that can induce the expression of nutrient transporters on NK cells while highlighting the imperative role of MyD88 in NK cell metabolism during infection." (PMID 34093543, 2021). "MyD88 had high transient expression 6 h after infection and then showed a stable expression pattern." (PMID 33193336, 2020).